TAS2R46 (taste 2 receptor member 46)
Description:
Receptor that may play a role in the perception of bitterness and is gustducin-linked. May play a role in sensing the chemical composition of the gastrointestinal content. The activity of this receptor may stimulate alpha gustducin, mediate PLC-beta-2 activation and lead to the gating of TRPM5 (By similarity). In airway epithelial cells, binding of bitter compounds increases the intracellular calcium ion concentration and stimulates ciliary beat frequency (By similarity).
Synonyms: T2R46; T2R54
Tractability: Small molecule: a structure with a bound ligand is known. Antibody: its Gene Ontology location is reachable by antibodies, with high confidence; UniProt predicts a signal peptide or a membrane-spanning region. PROTAC: a small molecule that binds it is known.
Target class: Membrane receptor; Taste receptor (taste family GPCR); Taste family G protein-coupled receptor
Gene: Protein-coding gene on chromosome 12 (11,061,365 to 11,062,294, reverse strand). Ensembl gene ENSG00000226761.
Subcellular location: Membrane; Cell projection, cilium membrane
Pathways (Reactome):
Signal Transduction: Class C/3 (Metabotropic glutamate/pheromone receptors); G alpha (i) signalling events
Sensory Perception: Sensory perception of sweet, bitter, and umami (glutamate) taste
Gene Ontology:
Molecular function: bitter taste receptor activity; G protein-coupled receptor activity
Biological process: detection of chemical stimulus involved in sensory perception of bitter taste; G protein-coupled receptor signaling pathway; sensory perception of taste
Cellular component: membrane; plasma membrane; ciliary membrane
Genetic constraint (gnomAD): Loss-of-function variants: 0 observed, 0.47 expected, observed/expected ratio (o/e) 0, 90% interval 0 to 1.84. That is too few expected variants to judge how well the gene tolerates losing a copy. Missense variants: 361 observed, 346.96 expected, observed/expected ratio (o/e) 1.04, 90% interval 0.95 to 1.13. Synonymous variants: 123 observed, 120.89 expected, observed/expected ratio (o/e) 1.02, 90% interval 0.88 to 1.18.
Homologues: Orthologues: chimpanzee TAS2R46 (98% identical), dog CAFA-T2R43 (61% identical), mouse Tas2r120 (48% identical), rat Tas2r120 (46% identical), rat Tas2r136 (45% identical), mouse Tas2r136 (44% identical). Paralogues in human: TAS2R43 (88% identical), TAS2R30 (85% identical), TAS2R31 (85% identical), TAS2R20 (69% identical), TAS2R50 (68% identical), TAS2R19 (67% identical), TAS2R14 (44% identical), TAS2R13 (44% identical), TAS2R9 (38% identical), TAS2R7 (37% identical), TAS2R10 (35% identical), TAS2R8 (35% identical), and 11 more.
Diseases named in the same sentence as TAS2R46 in open-access papers:
TAS2R46 is named in the same sentence as 6 diseases in open-access papers, as found by Europe PMC text mining. Sharing a sentence is not in itself a finding about the gene and the disease. The quoted sentences say what the papers report.
inflammatory bowel disease (2 papers, 2021 to 2024). A spectrum of small and large bowel inflammatory diseases of unknown etiology. "Berberine, which acts as an agonist for TAS2R38 and TAS2R46, has the ability to decrease inflammatory reactions and has been used for a long time in treating inflammatory bowel disease." (PMID 38397921, 2024).
TAS2R46 also shares sentences with these, for which no sentence is quoted: cancer (2 papers); breast carcinoma (1); glioma (1); invasive carcinoma (1); melanoma (1).